AR (androgen receptor)
Diseases named in the same sentence as AR in open-access papers (continued):
Sharing a sentence is not in itself a finding about the gene and the disease.
prostate carcinoma (continued). "Moreover, AR mediates distinct transcription programs in CRPC from that in castration-naive prostate cancers." (PMID 23896594, 2013). "In addition to LCA-mediated inhibition of cell viability, we assessed the ability of lower concentrations of LCA to inhibit the AD proliferation of AR positive LNCaP prostate cancer cells when stimulated with DHT." (PMID 23940835, 2013). "Current therapy used for prostate cancer targets either androgen production or AR activity." (PMID 23724033, 2013). "Resistance during prostate cancer therapy is mainly due to the marked increase in AR expression." (PMID 23824300, 2013). "The persistent capability of CRPC to become resistant to various means of suppression of AR signalling suggests that a multipronged approach to cancer treatment is required and leads to the research question: what drives prostate cancer aggressiveness and CRPC progression?" (PMID 23573093, 2013). "AR stimulates the expression of TMPRSS2: ERG, a common gene fusion associated with prostate cancer." (PMID 23466879, 2013). "It was also established that CpG methylation and histone acetylation may play important roles in the regulation of the AR, especially in prostate cancer cells." (PMID 24151599, 2013). "However, Chen and colleagues demonstrated that modest overexpression of AR also results in less specific ligand recognition on prostate cancer, indicating AWS can be expected in more cases with disease progression against anti-androgen administration." (PMID 23896594, 2013). "In the present study, we discovered two new lipid and cholesterol anabolism regulated miRNAs, miR-185 and 342, that blocked the SREBP-lipogenesis-cholesterogenesis, decreased AR expression, inhibited tumorigenicity and induced apoptotic death in prostate cancer cells." (PMID 23951060, 2013). "The androgen receptor (AR) signalling pathway may play a crucial role in the early development of prostate cancer, as well as in the development of androgen-independent disease that fails to respond to hormone deprivation therapies." (PMID 24282788, 2013). "Therefore, Casodex induces a DNA damage response in prostate cancer cells with wild-type AR (LAPC4 cells) or mutant AR (LNCaP cells)." (PMID 23363843, 2013). "In addition, the AR transcription program in primary human tissue is divergent from that in cultured prostate cancer cells." (PMID 23887938, 2013). "Thus, despite androgen ligand depletion, AR suppression further reduces prostate cancer cell growth." (PMID 23704919, 2013). "We confirmed that AR directly regulates c-Myc transcription in a ligand-independent manner, that AR and c-Myc suppression reduces ligand-independent prostate cancer cell growth, and that ectopic expression of c-Myc attenuates the anti-growth effects of AR suppression." (PMID 23704919, 2013). "AR plays a pivotal role in prostate cancer development and progression." (PMID 23359804, 2013). "However, AR knockdown by siRNA or shRNA requires treatment of prostate cancer cells over a period of several days." (PMID 23437213, 2013). "That prostate cancer can spontaneously acquire gain-of-function mutations in AR (rather than acquiring mutations that simply preclude inhibitor binding) underscores the special challenge in pharmacologically overcoming this mechanism of resistance." (PMID 23580326, 2013). "Piperine treatment also disrupted androgen receptor (AR) expression in LNCaP prostate cancer cells." (PMID 23824300, 2013). "While there is evidence that single targeting of either AR or PKARIα has tumor-inhibitory potential, the data presented in this study are the first showing the effects of combined targeting of these two molecules in prostate cancer in vivo." (PMID 23736698, 2013). "The androgen receptor (AR) plays a critical role in the proliferation of prostate cancer cells." (PMID 23437213, 2013).
prostate carcinoma (continued). "Given that the AR activates metabolic networks and regulates ER functions, we hypothesized that prostate cancer cells might exhibit increased expression of HBP enzymes." (PMID 23724116, 2013). "Notably, emodin has been shown to downregulate androgen receptor (AR) and inhibit prostate cancer growth, suggesting that there is a connection between anthraquinone derivatives and steroid receptor in hormone-related cancers." (PMID 23864887, 2013). "AR target genes have been established as candidate oncogenes and biomarkers in prostate cancer and in recent years chromatin immunoprecipitation coupled to high-throughputsequencing (ChIP-seq) and expression profiling has enabled an unbiased identification of AR-driven genenetworks." (PMID 23724116, 2013). "Thus, inhibiting intracellular AR signaling within prostate cancer cells has been a major focus of prostate cancer research, resulting in a variety of chemical inhibitors targeting AR signaling which are used in the clinic." (PMID 23326489, 2013). "The androgen receptor (AR) is the principal therapeutic target in prostate cancer." (PMID 23704919, 2013). "Moreover, SKIP augmented AR-dependent transcription with two ARE-containing reporters in prostate cancer PC3 cells." (PMID 23566155, 2013). "AR also plays important roles in the development, progression, and metastasis of prostate cancer." (PMID 23466879, 2013). "In this study, we explore the relationship of p68 and β-Catenin in PCa to assess their potential co-operation in AR-dependent gene expression, which may be of importance in the development of castrate resistant prostate cancer (CRPCa)." (PMID 23349811, 2013). "The androgen receptor (AR) is a member of the nuclear hormone receptor superfamily that regulates male sexual development, and is a major player in the pathogenesis and progression of prostate cancer." (PMID 23566155, 2013). "Therapies targeting the androgen-receptor signaling axis have been used for the treatment of prostate cancer with various strategies and may be suitable for application in the treatment of UUTUCs." (PMID 23599788, 2013). "Androgen receptor (AR), a member of the nuclear receptor (NR) superfamily, functions as a ligand-dependent transcription factor that plays a key role in the growth and maintenance of the normal prostate and the onset and progression of prostate cancer." (PMID 23887938, 2013). "Furthermore, the role of AR in promoting cancer is well characterized in prostate cancer with multiple mechanisms involved, including cell cycle regulation, apoptosis and kinase signals." (PMID 23599788, 2013). "In fact, it has been reported that certain cofactors can enhance AR transactivation in the presence of non-androgenic steroids and that deregulation of these cofactors had been implicated in prostate cancer evolution to androgen independence." (PMID 24167630, 2013). "Besides this well described effect in tumor cells there is convincing evidence that taxane therapy also interferes with androgen receptor (AR) in prostate cancer cells." (PMID 24260253, 2013). "Nuclear localization of β-Catenin may also result in increased complexes between AR and β-Catenin in prostate cancer cells, changing target gene activation." (PMID 23300485, 2013). "Interestingly, the expression of both GFPT1 and UAP1 was increased by ∼50% in AR-positive prostate cancer cell lines LNCaP and VCaP compared to normal prostate cells PNT2 and RWPE-1." (PMID 23724116, 2013). "A plausible explanation for this interference can be related to the antiandrogenic action (AR antagonist) of cimetidine since studies focusing on the effects of AR on NF-kB activity in the prostate cancer cell lines have demonstrated that NF-kB activity depends on the availability of androgens." (PMID 23570504, 2013). "MiR-185 and 342 also reduced AR mRNA and protein expression in prostate cancer cells." (PMID 23951060, 2013).
prostate carcinoma (continued). "Thus, c-Myc contributes to AR’s effects on promoting ligand-independent prostate cancer cell survival." (PMID 23704919, 2013). "The androgen receptor is currently the major hormonal target for prostate cancer treatment." (PMID 24376711, 2013). "This is also consistent with previous report that HOXB13 acts as repressor of androgen receptor signaling in prostate cancer, which may affect BRCA1 (cofactor associated with AR)." (PMID 23630576, 2013). "We propose the model that moderate AR gain in a TMPRSS2:ERG fusion-positive primary prostate cancer might synergistically enhance the expression of ERG, which gives growth advantage to those cells with moderate AR gain." (PMID 24098661, 2013). "At early stage, the prostate cancer is influenced markedly by androgen acting through the androgen receptor (AR) and, clinically, could be treated with surgical castration, radiation, or antiandrogen therapy." (PMID 23476140, 2013). "Finally, a PAC120 prostate cancer mouse model treated with streptozotocin (STZ) was used to evaluate in vivo the effects of hyperglycemia on AR regulation and tumor growth." (PMID 24058525, 2013). "Moreover, AR and PKARIα were found to be co-expressed and co-activated in human prostate cancer tissue, suggesting that dual targeting of these two molecules is preferable to single treatment." (PMID 23736698, 2013). "The AR indeed has been shown to exhibit a critical function in proliferation of prostate cancer cells that is distinct from its function as a transcription factor; in CWR22R3 cells, the AR role in proliferation, but not its role as a transcription factor, is androgen-independent." (PMID 23437213, 2013). "A cell signaling pathway switch from AR to c-Met in prostate cancer may originate from the selective pressure of long-term androgen deprivation." (PMID 23877345, 2013). "In castration resistant prostate cancer cells Doc therapy upregulates AR whereas Pac decreases AR." (PMID 24260253, 2013). "We therefore tested, whether SKIP can also act as a co-regulator of androgen receptor (AR), which is critically involved in prostate cancer." (PMID 23566155, 2013). "An understanding of the mechanism of AR action in proliferation may lead to the development of more effective strategies for the treatment of prostate cancer." (PMID 23437213, 2013). "Presently, several reports identified miRNAs in AR signalling in the prostate cancer." (PMID 23451058, 2013). "In summary, AR may exert control over proliferation of prostate cancer cells through its interaction with pre-RC and DNA replication machinery." (PMID 23437213, 2013). "However, androgen dependent prostate cancer cells (LNCaP) were found to be more sensitive to piperine treatment due to downregulation of multiple targets such as AR, NF-kB and STAT-3 expression in these cells." (PMID 23824300, 2013). "To examine whether CCAR1 is directly involved in AR-mediated transcription, we performed ChIP assays in prostate cancer cells." (PMID 23887938, 2013). "Androgen signalling and AR are critical for all phases of prostate cancer." (PMID 23894469, 2013). "Previous clinical studies showed that prostate-specific antigen (PSA) plays an important tumor marker for prostate cancer in male and nandrolone phenpropionate is an androgen receptor agonist and previous study showed that it can decrease cell growth of prostate cancer LNCaP cells." (PMID 24565337, 2013). "In these two tissues, androgens/AR signaling are known to regulate the frequency and extent of male typical behaviors and the development, function, and homeostasis of the prostate as well as prostate cancer initiation and progression, respectively." (PMID 23405127, 2013). "Indeed, recent advances in transcriptome and genome revealed that AR is one of the most frequently altered genes in prostate cancer." (PMID 23896594, 2013).
prostate carcinoma (continued). "Indeed, AR expression has a complex relationship with senescence induction in prostate cancer cells, with a recent report showing that constitutive AR overexpression can also induce senescence, albeit via a p21-dependent rather than p16-dependent mechanism." (PMID 23840802, 2013). "In men, the benefits of short repeat number may exceed the costs (i.e. from prostate cancer), and as there appear to be fewer benefits of short repeat number for women, our findings appear to support a hypothesis of sexual conflict over AR CAGn." (PMID 23467468, 2013). "Collectively, these observations invoke the possibility that, besides its role as a transcription factor, AR may play a direct role in cell cycle regulatory events required for proliferation of prostate cancer cells." (PMID 23437213, 2013). "Despite the independence of constitutively-active AR variants from the HSP90 chaperone system, HSP90 inhibitors are likely to be effective in CRPC by targeting signaling by wild-type AR, missense AR mutants and other critical pathways required for growth and survival of prostate cancer cells." (PMID 23674566, 2013). "Notably, FOXA1, a pioneer factor in development and differentiation, has been suggested to interact with hormonal receptors (ER and androgen receptor) and play a role in breast cancer and prostate cancer, and even in tamoxifen resistance." (PMID 24355041, 2013). "Regulation of VEGF by zinc finger transcription factors, such as Sp1, and the importance of their interactions with AR, suggests that they may play a positive role in promoting angiogenesis and prostate cancer progression." (PMID 23369005, 2013). "Furthermore, castration-resistant growth of a prostate cancer xenograft model results in increased β-Catenin and AR expression, co-localization in the nucleus and physical interaction of the proteins." (PMID 23300485, 2013). "Therefore, it looks reasonable to target AR as a master regulator of androgen-dependent and -independent prostate cancer growth." (PMID 23896594, 2013). "Interestingly, SREBP1 was found to regulate the transcription of the androgen receptor (AR) gene, and to promote proliferation, migration and invasion in prostate cancer." (PMID 24203995, 2013). "Great interest has recently been shown in two new compounds, MDV3100, an antiandrogen specifically designed for use in AR-overexpressing prostate cancer, and abiraterone acetate, a CYP17A inhibitor that blocks steroid biosynthesis in the adrenal gland and possibly within the tumor." (PMID 23667504, 2013). "Moreover, expression of PFKFB2 is induced in LNCaP prostate cancer cells after androgen treatment by the direct recruitment of the ligand-activated androgen receptor to the PFKFB2 promoter." (PMID 24280138, 2013). "GATA-2 plays an important role in activating androgen receptor signaling in prostate cancer." (PMID 23516510, 2013). "The AR signaling is very important for proliferation and survival of prostate cancer cells." (PMID 23658830, 2013). "What is the role of AR-mediated phosphorylation of eIF2α in prostate cancer?" (PMID 23405127, 2013). "p23 could also be involved in the incidence of prostate cancer as a key component of the androgen receptor activity." (PMID 24278769, 2013). "Considering that the levels of androgen synthesized by prostate cancer cells seem to be sufficient to activate the androgen receptor (AR), the acquisition of this capacity is thought to be the fundamental mechanism in the development of the androgen resistant prostate cancer phenotype." (PMID 24093019, 2013). "Growth and development of aggressive prostate cancer depend on androgen induced AR function." (PMID 23476140, 2013). "SKIP augmented ligand- and AR-dependent transactivation in PC3 prostate cancer cells." (PMID 23566155, 2013). "Hence, with regard to therapy, one major question is how aberrant AR activation can be effectively prevented in prostate cancer cells." (PMID 23736698, 2013).
prostate carcinoma (continued). "The fact that androgen dependent prostate cancer cells are more sensitive to piperine treatment could be due to down regulation of AR which is critical for the survival of androgen dependent prostate cancer cells such as LNCaP cells that we used in this study." (PMID 23824300, 2013). "Co-regulators play crucial roles in modulating AR activity and consequently may be important in regulating aberrant activity of AR during prostate cancer progression." (PMID 23887938, 2013). "Further, ganetespib displayed robust antitumor efficacy in both AR-negative and positive xenografts, including those derived from the 22Rv1 prostate cancer cell line that co-expresses full-length and variant receptors." (PMID 23152004, 2013). "To search for factors that regulate the AR functions, we previously purified and cloned a novel AR-interacting protein (p44) that regulates expression of a subset of AR-target genes in the prostate and prostate cancer." (PMID 23145110, 2012). "The AR plays a key role in the development and progression of prostate cancer." (PMID 23087897, 2012). "Furthermore, Tip60 can function as a co-activator for a number of steroid hormone receptors including the AR, which is involved in the development and progression of prostate cancer (CaP)." (PMID 23056207, 2012). "Androgen receptor antagonists have been proved to be effective anti-prostate cancer agents." (PMID 22754355, 2012). "Also, highly metastatic, aggressive, and androgen-independent prostate cancer cells are more likely to exhibit an AR(−) and PSMA(−) genotype." (PMID 23041906, 2012). "AR amplification is not a common event in primary prostate cancer, but has been implicated in hormone resistance in CRPC." (PMID 22373240, 2012). "GASC1 colocalizes with androgen receptor (AR) in both normal prostate and prostate carcinomas." (PMID 23148692, 2012). "Considering the crucial role of AR pathway in human prostate cancer, these new findings may provide a scientific basis of developing new tanshinone-based therapeutic agents for prostate cancer via suppressing AR pathway." (PMID 23202971, 2012). "Using a specific AR antibody (PG-21, Millipore), an optimised staining protocol was developed using prostate cancer cell lines LNCaP (AR+VE) and PC3 (AR–VE), allowing identification of the highest concentrations of antibody to increase sensitivity whilst controlling for non-specific labelling." (PMID 23145034, 2012). "The activation of PKD1 and the reduction of β-catenin transcriptional activity by curcumin may also impact androgen receptor (AR) signaling in prostate cancer, since both PKD1 and β-catenin modulate AR function." (PMID 22523587, 2012). "We then investigated whether activation of AMPK by B-DIM could result in apoptotic cell death and inhibit the expression of prostate cancer signature proteins, such as AR and PSA." (PMID 23056607, 2012). "Since the AR is a major regulator of prostate cancer cell growth, we wanted to determine if any of the six selected kinases might affect growth through regulating the AR transcriptome." (PMID 22761715, 2012). "Previously considered to be androgen-independent, it is now emerging that these recurrent prostate cancers may still rely on AR signaling for growth and survival." (PMID 22614157, 2012). "The AR co-activators we suggested, and the AT rich environment of AR binding, should be further evaluated in biological experiments to validate their role and significance in prostate cancer." (PMID 23056316, 2012). "Interestingly, there is recently a paradoxical observation that the growth of some “androgen sensitive” human prostate cancer cells expressing androgen receptor can be inhibited by supraphysiologic levels of androgens." (PMID 21754927, 2012).